HIF1A (hypoxia inducible factor 1 subunit alpha)
Diseases named in the same sentence as HIF1A in open-access papers (continued):
Sharing a sentence is not in itself a finding about the gene and the disease.
chordoma (7 papers, 2010 to 2024). Chordomas are rare malignant tumors arising from embryonic remnants of the notochord in axial skeleton. "Since hypoxia is both a major characteristic of chordomas and a cause of radiotherapy failure, we mapped the hypoxic regions within spheroids using pimonidazole and HIF-1α staining." (PMID 33672032, 2021). "As NCs are resistant to hypoxia-related stress (in part due to high HIF-1α expression) and present metabolic adaptations to strive under harsh nutrient conditions, chordomas are inherently resistant." (PMID 39051200, 2024). "As HIF‐1α is well known to play a crucial role in response to hypoxia, we, therefore, detected the relationship between the expression of these TFs and HIF‐1α in chordoma tissues using the bulk RNA‐seq data." (PMID 39207055, 2024). "HDAC inhibition led to reduction in chordoma cell proliferation and invasion, and HIF-1α expression." (PMID 26247786, 2015). "We observed that chordoma cells propagated at low oxygen tension had a proliferative advantage and expressed both HIF-1α and its downstream target, VEGF." (PMID 26247786, 2015). "Recent studies have reported HIF-1α expression in the majority of chordoma samples examined, correlated with VEGF expression and tumour microvessel density." (PMID 25541962, 2014). "Although the over-expression of these transporters was a common phenomenon in chemoresistant tumor cells, we found that MRP1 and HIF-1α expression was upregulated in most chordoma tissues in comparison to normal tissues." (PMID 21143841, 2010). "Anaylsis of HIF-1α, MDR1 and MRP1 mRNA was conducted in CM-319 and chordoma by RT-PCR analysis using three pairs of primers designed for the human HIF-1α, MDR1 and MRP1 sequences." (PMID 21143841, 2010). "The aim of this study was to investigate the expression of three genes (MDR1, HIF-1α and MRP1) associated with resistance to chemotherapy and radiotherapy in chordoma and chordoma cell line CM-319." (PMID 21143841, 2010). "Chordomas that had high MRP1 expression were also likely to have high HIF-1α expression." (PMID 21143841, 2010). "Based on these findings, we speculate that in addition to independent CCN2 and HIF-1α induced pathways, there could be interaction between HIF-1α and CCN2 in chordoma cells, such that rCCN2 is decreasing HIF-1α activity under hypoxia but promoting HIF-1α activity under normoxia." (PMID 25541962, 2014). "Markers such as HIF-1α and factors involved with metabolic regulation (e.g., GLUT-1) have been suggested as prognostic markers for overall chordoma survival." (PMID 39051200, 2024). "Using immunohistochemical techniques, the expression of MDR1, HIF-1α and MRP1 was investigated in 50 chordoma specimen." (PMID 21143841, 2010). "Using RT-PCR and Western blot, the expression of MDR1, HIF-1α and MRP1 was investigated in chordoma and chordoma cell line CM-319." (PMID 21143841, 2010). "Expression of HIF-1α and MRP1 was observed in most chordoma specimen and CM-319 cell line; expression of HIF-1α correlated with MRP1." (PMID 21143841, 2010). "Expression of HIF-1α in chordoma was much higher than that in nucleus pulposus; expressiong of MRP1 in chordoma was also much higher than that in nucleus pulposus; but expression of MDR1 in chordoma was not different from that in nucleus pulposus." (PMID 21143841, 2010). "Although no change was detected in the expression of HIF1A, chordoma cells demonstrated a significant increase in the expression of both VEGF-A and GLUT1 in hypoxia compared to cells maintained in normoxia." (PMID 25541962, 2014). "HIF-1α and MRP1 may play a role in the multidrug resistance of chordoma to chemotherapy." (PMID 21143841, 2010). "The current results showed that MRP1was expressed in the membranous and intracellular regions; HIF-1α was expressed in the cell cytoplasmic and nuclear regions, whereas MDR1 was not expressed in the chordoma tissues or CM-319 cell." (PMID 21143841, 2010).
dysplasia (7 papers, 2007 to 2020). A usually neoplastic transformation of the cell, associated with altered architectural tissue patterns. "Gastric biopsy specimens of intestinal metaplasia, dysplasia and intestinal type adenocarcinoma show a progressively increased density and intensity of HIF-1α staining." (PMID 17179985, 2007). "There were significant differences in marker expression in adenocarcinoma compared with dysplasia for HIF-1α (P=0.014), HIF-2α (P=0.012), Ki67 (P=0.0001) and Epo-R (P=0.042)." (PMID 17437013, 2007). "The aim of this study was to investigate HIF-1α, HIF-2α, and ProExC expression in conjunctival intraepithelial neoplasia (CIN), to differentiate between metaplasia and dysplasia, and to access their value as diagnostic and prognostic immunohistochemical markers." (PMID 32458097, 2020). "In our previous study, we observed that the formation of microvessels, as well as the expression of pro-angiogenic factors HIF-1α and VEGF, was inhibited in dysplasia and SCC by Sal B." (PMID 21726465, 2011). "The expression of HIF-1α was strong or very strong in 60% of non-dysplastic lesions, 100% of low-grade dysplasia cases, 53% of high-grade dysplasia cases and 50% of invasive cancer cases." (PMID 30840126, 2019). "Consistent with this, positive HIF-1α immunostaining was also found in the parabasal to middle third layer of the benign cervical squamous epithelium and HIF-1α expression significantly increases in all grades of dysplasia." (PMID 21283817, 2011). "Our aim was to assess the immunohistochemical expression of hypoxia-inducible factor (HIF)-1α, HIF-2α, erythropoietin (Epo), Epo receptor (Epo-R), Glut-1 and vascular endothelial growth factor (VEGF) along with Ki67/MIB-1 in the Barrett's metaplasia–dysplasia–adenocarcinoma sequence." (PMID 17437013, 2007).
hematoma (7 papers, 2020 to 2024). A hematoma is a collection of blood from a vascular structure into an extravascular space. "Combined with the rapid decline in behavioral scores in the HBO group over time, they believe HBO enables hematoma absorption by supplying oxygen and promoting the expression of HIF-1a and VEGF." (PMID 39139771, 2024). "VEGF levels are significantly increased within hematoma fluid and neomembranes compared with serum samples, and its presence is associated with increased levels of TNF-α and hypoxia-inducible factor-1 α (HIF-1α), both of which are known as VEGF inducers." (PMID 35673314, 2022). "Hematoma prior to rebleeding was predominantly composed of myeloid subcluster 4, which was enriched for glycolysis and HIF-1α signaling." (PMID 33749664, 2021). "Many HIF-1α+ and VEGF+ microvessels were detected surrounding the hematoma following ICH in the enlarged profile." (PMID 36349188, 2022). "In the hematoma of CSDH patients, VEGF expression was significantly correlated to HIF-1α expression and VEGF concentration in the hematoma." (PMID 32328124, 2020). "In the XYK group, HIF-1α and VEGF decreased significantly, E3 ubiquitin-protein ligase parkin and 26S proteasome protein in the hematoma increased significantly, and the Ang-1/Ang-2 ratio increased significantly compared with the CSDH group." (PMID 32328124, 2020). "An increase in regulatory T helper cells and the expression of anti-inflammatory cytokine IL-10 were observed alongside an increase in angiogenic factors (HIF1a and HIF1a regulated genes), specifically within regenerative bone hematoma rather than soft tissue hematoma." (PMID 37833933, 2023).
Hydrocephalus (7 papers, 2015 to 2022). Hydrocephalus is an active distension of the ventricular system of the brain resulting from inadequate passage of CSF from its point of production within the cerebral ventricles to its point of absorption into the systemic circulation. "Neural cell-specific Hif-1α deficient mice exhibit a hydrocephalus accompanied by a reduction of neuronal cells and an impairment of spatial memory, indicating that HIF is crucial for brain development." (PMID 33154420, 2020). "We also calculated the Evans index to evaluate the degree of hydrocephalus, and it also revealed that the low-HIF-1α score patients exhibited more significant cerebroventricular expansion than that of high-HIF-1α patients." (PMID 36091021, 2022). "Notably, children with low HIF-1α scores were related to the hypothalamus involvement and hydrocephalus symptoms." (PMID 36091021, 2022). "In this study, we firstly identified HIF-1α as a pivotal regulator participating in the pathogenesis of ACP and found that it was significantly associated with clinical phenotypes including hydrocephalus and hypothalamus involvement based on clinical characteristics." (PMID 36091021, 2022). "Neural cell-specific knockout of Hif1α using Nestin-Cre driver causes massive apoptosis in the cerebrum at E19, resulting in hydrocephalus at P70, while no gross morphological differences can be observed in E15 embryos." (PMID 35361248, 2022). "Notably, the low-HIF-1α score cohorts included all children patients and exhibited more severe clinical phenotypes including hypothalamus involvement and hydrocephalus." (PMID 36091021, 2022). "Additionally, conditional ablation of HIF1-α in adult mouse brain resulted in hydrocephalus, decreased neurogenesis (partly due to an increase in apoptosis) and deficits in spatial memory." (PMID 26476335, 2015). "Although the occurrence of cerebral hypoxia contributed to the development of chronic adult hydrocephalus, patients with a high expression of HIF-1α were all adults and no hydrocephalus occurred in this cohort." (PMID 36091021, 2022). "Interestingly, the lack of Hif1a in brain results in alterations similar to the ones determined in the present study, such as reduced neurogenesis and hydrocephalus." (PMID 36590296, 2022).
infantile hemangioma (7 papers, 2010 to 2024). "Taken together, we demonstrate that LncRNA-MCM3AP-AS1 promotes the progression of infantile hemangiomas by increasing the glycolysis via regulating miR-138-5p/HIF-1α axis." (PMID 34660700, 2021). "The other showed that ACE2 and HIF1α balanced each other in infantile hemangioma in vitro." (PMID 39273283, 2024). "In addition, β2-AR antagonist propranolol has been shown to regress infantile hemangiomas in a HIF-1α-dependent manner." (PMID 28855859, 2017). "Up-regulation of HIF-1α and down-regulation of VEGFR1 is reported to be characteristic to infantile hemangioma while down-regulation of VEGFR1 is also seen in angiosarcoma, and such abnormal expression of angiogenic factors are thought to play some role in their pathogenesis." (PMID 21179471, 2010).
lupus nephritis (7 papers, 2017 to 2025). Glomerulonephritis in the context of systemic lupus erythematosus. "In patients with lupus nephritis, upregulation of miR-31-5p has been observed and thought to inhibit HIF-1α thereby ameliorating the nephritis." (PMID 40036580, 2025). "In RA, HIF-1α induces both angiogenesis and proinflammatory mechanisms, and in lupus nephritis larger amounts of HIF-1α in both glomerular and tubulointerstitial areas evaluated by immunohistochemical staining have been observed." (PMID 28484714, 2017). "This is different from previous studies in humans, where significantly higher concentrations of urine HIF-1α protein were present in lupus nephritis patients; furthermore, there were also significantly higher concentrations of urine HIF-1α mRNA in CKD patients." (PMID 39748872, 2024). "There was a significant positive correlation between Hk2 and Hif1a and Il1b transcripts in MRL-lpr kidneys with lupus nephritis, implicating HIF1α-induced glycolysis in the induction of autoantibody-mediated inflammation in vivo." (PMID 32541026, 2020). "Here we focused on acute models of nephritis, but future studies will be required to investigate the effect of longer-term HIF1α or glycolysis inhibition in chronic models of nephritis, such as in NZB/W mice, to determine the potential of these therapies for treating patients with lupus nephritis." (PMID 32541026, 2020).
malaria (7 papers, 2010 to 2023). Malaria is a serious and sometimes fatal disease caused by a parasite that commonly infects a certain type of mosquito which feeds on humans. "DEC-1 labelling of nuclei was observed in both controls and malaria cases, so HIF-1α stabilization in the nucleus of cells in the brain at some point during the disease course cannot be ruled out." (PMID 20716170, 2010). "Similarly, within B cell subsets, malaria drove a significant increase in HIF1A expression, which has previously been shown to be a critical transcription factor for the induction of IL-10 producing Bregs in mouse models." (PMID 37968278, 2023). "Finally, they report that the effect of different oxygen levels on the infection of liver cells by malaria parasites is partly due to the activation of the HIF-1α intracellular oxygen sensing signaling pathway." (PMID 24291761, 2014). "For example, while higher levels of HIF-1α mRNA expression have been identified in placental tissues, VEGFA expression was downregulated in malaria patients." (PMID 37375100, 2023). "HIFs showed limited protein expression and/or translocation to cell nuclei in severe malaria, but DEC-1, which is more stable and regulated by HIF-1α, was observed." (PMID 20716170, 2010). "It therefore appears that widespread persistent stabilization of HIF-1α is not occurring in severe malaria cases." (PMID 20716170, 2010). "No reactivity for HIF-1α was observed in any of the malaria cases despite multiple attempts using different protocols and antibodies, and despite very good control staining." (PMID 20716170, 2010). "However, increased HIF-1α and VEGFA has not been the consensus in malaria patients." (PMID 37375100, 2023).
non-alcoholic steatohepatitis (7 papers, 2020 to 2025). "HIF activation also exhibits anti- and proinflammatory effects regulating the activity of immune cells, and HIF1A can induce nonalcoholic steatohepatitis and further cause autophagy damage to macrophages by mediating NF-κB activation and MCP-1 production." (PMID 35659268, 2022).
parasite infection (7 papers, 2013 to 2026). "Among parasitic diseases, the upregulation of HIF1α mRNA expression was also observed in the renal tissue of hosts with malaria." (PMID 39543383, 2024). "Parasite infection promotes the increased expression and activation of HIF-1α, and macrophages in which HIF-1α is silenced using siRNA control intracellular parasite replication, suggesting that protozoa can use this pathway to survive and proliferate inside the cell." (PMID 35585983, 2022). "Hif1a mRNA levels were also elevated in the ME/ hypothalamus after parasite infection." (PMID 34587172, 2021). "Among other Apicomplexan infections, host HIF-1α has been shown to be essential for Toxoplasma gondii survival and growth in host cells cultured at physiological oxygen levels (3% O2), and is also necessary for the maintenance of Leishmania amazonensis parasitemia in human macrophages in vitro." (PMID 24291761, 2014). "Finally, following parasite infection, miR-210 abundance was enhanced in HIF-1α-dependent manner, though it did not contribute to inhibiting anti-apoptotic pathways through pro-apoptotic caspase-3 regulation." (PMID 24098824, 2013). "Moreover, the attenuated increase in parasite infection that we observed in LPS-primed HIF-1α mutant iPSC-CMs, and in iPSC-CMs treated with both LPS and 2DG suggests that LPS effects are largely mediated by HIF-1α and glycolysis effects on cardiomyocyte metabolism." (PMID 36814444, 2023).
periodontal disease (7 papers, 2015 to 2025). "Gingival crevicular fluid levels were found to be affected by disease status, indicating that the TNF-α/HIF-1α/VEGF pathway might play a role in periodontal disease pathogenesis." (PMID 39822781, 2024). "We hypothesized that the combination of both stimuli disturbs the periodontal homeostasis leading to a progression of periodontal diseases as a consequence of the activation of NF-κB and HIF-1α." (PMID 25861162, 2015). "The activations of HIF-1α and NF-κB in PDL cells and periodontal diseases are displayed under the hypoxic situation accompanied with lipopolysaccharide stimulation." (PMID 35221795, 2022). "Higher levels of HIF-1α and VEGF have been observed in periodontal disease, suggesting that the HIF-1α pathway might be activated in advanced disease stages, possibly influenced by bacterial endotoxins and inflammatory cytokines." (PMID 39822781, 2024).
transient cerebral ischemia (7 papers, 2011 to 2021). "Increasing HIF-1α protein stability reduces brain injury after transient cerebral ischemia." (PMID 25976178, 2015). "At the same time, transcriptional upregulation of heme oxygenase-1 in RVLM by hypoxia-inducible factor-1α (HIF-1α) plays a pro-life role in experimental brain death, and HIF-1α is subject to sumoylation activated by transient cerebral ischemia." (PMID 21390240, 2011).
allergic asthma (6 papers, 2012 to 2026). A asthma with a basis in a pathological type I hypersensitivity reaction. "Based on these observations, we have investigated whether mTOR is associated with HIF-1α-mediated VEGF expression in allergic asthma." (PMID 24312355, 2013). "Since the allergic asthma has intimate links with HIF-1α, further investigation can be focused on the interaction between TH and T cells, and how HIF-1α functions during the BMMC-mediated inflammation process." (PMID 34421593, 2021). "HIF-1α and VEGF were locally up-regulated in a murine AR model in a manner similar to that observed in lungs following allergic asthma." (PMID 23133644, 2012). "In an OVA-induced murine model of allergic asthma, IGFBP-3 expression was decreased, and levels of HIF-1α and HIF-2α in nuclear protein extracts from lung tissues were increased at 48 h after OVA inhalation compared to levels measured 48 h after saline inhalation." (PMID 30150897, 2018).
ameloblastoma (6 papers, 2019 to 2025). The most common odontogenic tumor, arising from the epithelial component of the embryonic tooth and usually affecting the molar-ramus region of the mandible or maxilla. "Conversely, within solid regions of ameloblastomas, HIF-1α expression was solely localized to the nuclei." (PMID 39657933, 2025). "Previous studies have demonstrated that hypoxia-induced factor alpha 1 (HIF-1α) and activated caspase-3 contribute to tumour invasiveness and cytogenesis in ameloblastoma." (PMID 34987583, 2021). "Considering the previous studies, our research group observed that HIF-1α is expressed in the nucleus of neoplastic cells in solid areas of the ameloblastoma, whereas it was expressed in the cytoplasm and nucleus in cystic regions." (PMID 34987583, 2021). "As shown in ameloblastoma, transcription and post-transcription factors such as hypoxia-inducible factor 1α (HIF-1α), ADAM-12, and NOTCH1 are directly involved in an HB-EGF autocrine amplification loop and facilitate local tumor invasiveness." (PMID 31936715, 2020). "The ameloblastoma samples showed higher immunoexpression of HIF-1α, MMP-2, VEGF, and VEGFR-2 when compared to the dental follicles and calcifying odontogenic cysts." (PMID 33067558, 2020). "To clarify the role of HIF‐1α in ABs and ACs, we performed the in vitro hypoxic culture using a human ameloblastoma cell line, AM‐1." (PMID 31674718, 2019). "Our group showed an interesting pattern of HIF-1α immunostaining in ameloblastoma." (PMID 36338393, 2022). "We found that hypoxia‐induced HIF‐1a and ZEB1 are critical for the malignant transformation of ameloblastoma via TGF‐beta‐dependent EMT." (PMID 31674718, 2019). "Our results show higher immunoexpression of HIF-1α, MMP-2, VEGF, and VEGFR-2 in ameloblastomas when compared to calcifying odontogenic cysts and dental follicles, suggesting that the relationship between these proteins may contribute to the behaviour of this neoplasm." (PMID 33067558, 2020).